IL1B (interleukin 1 beta)
Diseases named in the same sentence as IL1B in open-access papers (continued):
Sharing a sentence is not in itself a finding about the gene and the disease.
Muckle-Wells syndrome (16 papers, 2009 to 2024). "Mice carrying the Muckle-Wells Syndrome gene variant A350V develop Muckle-Wells syndrome-like systemic inflammation due to overactivation of the NLRP3 inflammasome and IL-1β production." (PMID 37744356, 2023). "It is well-established that IL-1β production plays a critical role in the generation of protective anti-fungal immunity; however, IL-1β dysregulation is associated with IBD and CAPS such as Muckle-Wells syndrome." (PMID 31139177, 2019). "Using NLRP3 mutant mice expressing Muckle-Wells syndrome (MWS) mutation at A350V we addressed if quercetin still could inhibit IL-1β secretion." (PMID 28148962, 2017). "Unopposed expression of IL-1β has been shown to induce sensorineural deafness in patients with Muckle-Wells syndrome, an autoinflammatory disorder." (PMID 19401759, 2009). "Reduction of mononuclear cell secretion of IL-1β was observed following anakinra therapy and correlated with hearing restoration in a patient with Muckle-Wells syndrome." (PMID 19401759, 2009). "Excessive IL-1β release in PBMC from Muckle-Wells Syndrome MWS (OMIM entry 191900) patients could also be blocked by BTK inhibitors." (PMID 29167667, 2017).
nasal polyps (16 papers, 2011 to 2023). "Polymorphisms in the IL-1 receptor antagonist gene (IL1RN) are associated with CRS, and in CF, elevated IL-1β is associated with the presence of nasal polyps (41, –, 44)." (PMID 36094193, 2022). "Thus, BITC may be a useful novel therapy for LPS-associated inflammatory pathological conditions, including nasal polyps (NP), by targeting inflammasome-mediated IL-1β production signaling pathways." (PMID 35163151, 2022). "IL-1β increased the secretion of CCL5 from nasal polyp fibroblasts, resulting in the attraction of monocytes, eosinophils and memory T-cells, and the recruitment and trans-endothelial migration of these cells to the inflammation site." (PMID 35008843, 2021). "In contrast, another study found increased levels of IL-1β along with IL-6 and IL-8 and a high percentage of nasal polyps." (PMID 34208325, 2021). "In summary, our study showed that the p38 MAPK and JNK signal pathways are involved in regulating the expression of GR isoforms in IL-1β-induced nasal polyps in vitro, as their activation resulted in a decrease of GRα/GRβ ratio." (PMID 25632272, 2015). "IL-1β induced a decrease in the GRα/GRβ ratio in a time-dependent manner in cultured nasal polyps in vitro." (PMID 25632272, 2015). "The GRα/GRβ ratio decreased in a concentration-dependent manner in nasal polyp tissue induced by IL-1β." (PMID 25632272, 2015). "Our results demonstrated that the imbalanced expression of GR isoforms in nasal polyp tissue induced by IL-1β in vitro is mediated through the p38 MAPK and JNK signal pathways." (PMID 25632272, 2015). "IL-1β induced a decrease in the GRα/GRβ ratio in a dose-dependent manner in cultured nasal polyps in vitro." (PMID 25632272, 2015). "Low expression of GRα (94 kDa) and GRβ (90 kDa) was detected by using Western blot in the cultured nasal polyp tissue of the control group (0 ng/mL IL-1β), and it showed that the expression level of GRβ was lower than that of GRα." (PMID 25632272, 2015). "In this study, a GC resistance model of nasal polyps induced by interleukin-1 beta (IL-1β) in vitro was developed to measure the relationship between the expression of GR isoforms and p38 MAPK and JNK signal transduction pathways." (PMID 25632272, 2015). "The mRNA and protein expression of GRα and GRβ in the IL-1β-induced nasal polyp tissues increased in a concentration-dependent manner (depending on IL-1β concentration), and the expression of GRβ increased more significantly than that of GRα." (PMID 25632272, 2015). "The mRNA and protein expression levels of GRα, GRβ and key enzymes of the p38 MAPK and JNK pathways increased both in time- and concentration-dependent manners in IL-1β-induced nasal polyp tissue." (PMID 25632272, 2015). "An in vitro model of Glucocorticoid resistance was established by inducing nasal polyp tissue with IL-1β." (PMID 25632272, 2015). "The final objectives of this research were to verify whether IL-1β produced by endotoxin-stimulated activation of inflammasomes induces fibrosis and to reveal the reaction mechanism in the growth of nasal polyps (NPs)." (PMID 35163151, 2022). "These BITC-mediated modulatory effects on IL-1β production may have therapeutic potential for inflammasome-mediated disorders such as a nasal polyp." (PMID 35163151, 2022). "Besides its inflammatory effects, IL-1β is responsible for glucocorticoid resistance in nasal polyp tissue, rendering local treatment more complex." (PMID 35008843, 2021). "Thus, our data about the decreased expression of IL-1α just proves the probably insignificant role of this IL in the inflammation of nasal polyps or indicates the possible compensation for the expression of other IL-1 type (IL-1β) in case of the disease." (PMID 34208325, 2021).
nasal polyps (continued). "In a study using cultured fibroblasts from healthy nasal mucosa and nasal polyps from patients with aspirin-tolerant and -sensitive asthma, PGE2 concentration was lower in patients with both aspirin-tolerant and -sensitive nasal polyps after IL-1β stimulation, than in the controls." (PMID 32182661, 2020). "It has been reported that not only murine ILCs but also human blood and nasal polyp derived ILC2s could trans-differentiate by stimulation of a set of cytokines (IL-1β, IL-13, and TGF-β)." (PMID 32223753, 2020). "In our own study, we found that IL-1β could induce a reduction of the GRα/GRβ ratio in dose- and time-dependent manners in cultured nasal polyps in vitro." (PMID 25632272, 2015). "We also found that after cultured nasal polyps were induced with the same set of IL-1β concentrations, the p38 MAPK and JNK signal pathways were also activated, as the expression of key enzymes of both pathways increased in a similar concentration-dependent manner." (PMID 25632272, 2015). "No noticeable changes of GR isoforms and GC affinity were observed after PI3K, ERK or PKC pathways were blocked, which suggests that these pathways were not involved in the regulation of GR expression and GC sensitivity in the IL-1β-induced nasal polyps in vitro." (PMID 25632272, 2015). "In this study, IL-1β was used to induce cultured nasal polyp tissues in vitro." (PMID 25632272, 2015). "Although our study showed that both the p38 MAPK and JNK signal pathways were involved in the regulation of GR isoform expression in IL-1β-induced nasal polyps in vitro, more research needs to be carried out in order to determine how these two pathways regulate this process." (PMID 25632272, 2015). "Our results showed that PVP-I can inhibit the inflammation-induced IL-1β secretion and IRF3/7 activation, and 27 cytokines in airway epithelial cells and pHNECs from nasal polyps." (PMID 35256715, 2022). "IL-1β led to higher phospho-p38 MAPK and phospho-JNK expression at the protein and mRNA levels in a concentration-dependent manner in nasal polyp tissues in vitro." (PMID 25632272, 2015). "In addition, increased expression of the EP2 receptor in fibroblasts after IL-1β stimulation was identified only in normal mucosa, but not in nasal polyps from either aspirin-tolerant or -sensitive patients." (PMID 32182661, 2020). "Although a recent study showed that hypoxia might induce Cyr61 and IL-8 secretion in nasal polyp fibroblasts, no direct evidence demonstrated that Cyr61 induces IL-8 production under an inflammatory environment via an IL-1β/TNF-α independent pathway." (PMID 24517278, 2013).
Peptic ulcer (16 papers, 2013 to 2025). The term peptic ulcer refers to acid peptic injury of the digestive tract, resulting in mucosal break reaching the submucosa. "There was a significant elevation in the serum IL-1β levels in the peptic ulcer untreated rats by 2.27 fold compared to normal rats." (PMID 36542210, 2022). "IL-1β is a key factor in triggering and amplifying inflammation, and a low IL-1β level coupled with a high TNF-α level may increase the risk of peptic ulcer disease in H. pylori infections." (PMID 39354365, 2024). "Additionally, there was a significant increase in the serum levels of TNF-α and IL-1β in untreated peptic ulcer rats." (PMID 36542210, 2022). "The association between a low IL-1β level and an increased TNF-α level might be considered a risk factor for peptic ulcer disease in the setting of H. pylori infection." (PMID 35884067, 2022). "Moreover, the authors concluded that the association between a decrease in the IL-1β level, along with an increase in TNF-α, might be considered a risk factor for peptic ulcer disease in the setting of H. pylori infection." (PMID 35884067, 2022). "A study in 2023 on peptic ulcer disease found that the expression of NLRC4, NLRP12, IL-18 and IL-1β decreased significantly in patients of peptic ulcer disease compared with those of only H. pylori-associated gastritis." (PMID 37833958, 2023). "Infiltration of macrophages and neutrophils, and the release of pro-inflammatory cytokines (such as TNF-α, IL-1β and MCP-1) significantly affect the healing and recurrence of peptic ulcer." (PMID 29095895, 2017). "A decrease in IL-1β and IFN-γ levels combined with an increase in IL-4 levels indicates its potent anti-inflammatory effect, which probably plays a key role in preventing peptic ulcer relapses." (PMID 40283939, 2025). "Inflammation is a pivotal pathological reaction of ethanol-related peptic ulcer, which is mainly characterized by increased secretion of diverse proinflammatory factors, such as TNF-α, IL-6, and IL-1β, and inhibition of the production of anti-inflammatory cytokines such as IL-10." (PMID 32325708, 2020). "A recent study showed that the CYP2C19 genotype, unlike MDR1 and IL-1B genotypes, had an impact on the efficacy of Helicobacter pylori eradication in peptic ulcer patients treated with pantoprazole in triple therapy administrations." (PMID 23617933, 2013). "Nevertheless, a recent study pointed out that IL-1β might be involved in the pathogenesis of peptic ulcers regardless of the presence of H. pylori infection." (PMID 35884067, 2022).
skin cancer (16 papers, 2014 to 2025). "NLRP1 gain-of-function mutations are responsible for constitutive secretion of IL-1β by keratinocytes, which enable skin inflammation and epidermal hyperplasia, and a predisposition to skin cancer." (PMID 32635472, 2020). "As shown in the 3-methylcholanthrene (3-MCA)-induced skin cancer model, IL-1β-deficient animals have fewer intra-tumor neutrophils, while IL-1RA-deficient mice have dense infiltrate, suggesting that IL-1β produced in tumors can recruit neutrophils." (PMID 32635472, 2020). "Also in support of the notion that IL-1β promotes tumorigenesis, gain-of-function mutations in NLRP1 caused constitutive activation and secretion of IL-1β in keratinocytes, resulting in skin inflammation that made the patients more susceptible to skin cancer." (PMID 38391959, 2024). "However, the roles of the inflammasomes and IL-1β in skin cancer vary, depending on the types of cells." (PMID 33686176, 2021). "It is a safe agent preventing UVB-induced skin cancer via targeting inflammatory mediators (lowering COX-2, PGE2, PCNA, TNF-α, IL-1β, and IL-6 levels), cell cycle regulators (CDK inhibitor upregulation), and cell survival signals (cyclins D1, D2, E2 and CDKs2, 4, 6 inhibition)." (PMID 40943669, 2025).
ankylosing spondylitis (15 papers, 2006 to 2025). An autoimmune chronic inflammatory disorder characterized by inflammation in the vertebral joints of the spine and sacroiliac joints. "Moreover, both conditions share key aspects of immune regulation, notably elevated T-cell-mediated responses and inflammatory cytokines like TNFα, IL-6, and IL-1β, reflecting an increased cardiovascular disease risk in ankylosing spondylitis patients." (PMID 39131703, 2024). "Ankylosing spondylitis is characterized by the higher release of NETs from polymorphonuclear leukocytes containing bioactive IL-17A and IL-1β, which can in turn mediate the osteogenic differentiation of MSCs into bone-forming cells." (PMID 39273077, 2024). "Based on our ELISA data, we observed significant increases in multiple pro-inflammatory factors (IL-17, IL-23, TNF-α, IL-1β, and IL-18) in the serum of mice with ankylosing spondylitis (AS) compared to the control group (p < 0.05)." (PMID 39857593, 2024). "Given that we previously published ERAP1 deficient mice have enhanced bony fusions in a phenotype similar to ankylosing spondylitis, and our results demonstrating that ERAP1-deficient BMDMs have elevated IL-1β production, we wished to study the impact of MSU crystals on ERAP−/− cells." (PMID 35246034, 2022). "There may be some false positive results, but it has been able to explain the trend of IL-1A and IL-1B in patients with ankylosing spondylitis." (PMID 28423679, 2017). "The efficacy was assessed using subjective tools [Bath Ankylosing Spondylitis Disease Activity Index (BASDAI) and Neck Disability Index (NDI) questionnaires) and objective measures (clinical markers, NLRP3 and IL-1β)." (PMID 40667507, 2025).
Barrett esophagus (15 papers, 2011 to 2025). Esophageal lesion lined with columnar metaplastic epithelium which is flat or villiform. "A transgenic mouse model in which the human IL-1β gene is overexpressed in the esophagus reflects the pathology underlying the progression toward Barrett’s esophagitis in humans, i.e., from low-grade and high-grade dysplasia to esophageal adenocarcinoma." (PMID 33671768, 2021). "It has been well known that Barrett's esophagus is the major cause of esophageal adenocarcinoma, during the progression, cytokines play critical role, for instance, increased expression of IL-1β in mouse leads to esophageal inflammation and esophageal adenocarcinoma in IL-1β transgenic mouse model." (PMID 28402280, 2017). "EndMT is triggered by the co-culture of ECs with esophageal adenocarcinoma cells expressing high levels of IL-1β and TGF-β2." (PMID 40650130, 2025). "The IL-1β transgenic mouse model (ED-L2-IL-1β) was initially characterized by our group as a model of Barrett’s Esophagus (BE)-like metaplasia, glandular dysplasia and adenocarcinoma (12–18 M) affecting the squamo-columnar junction of the murine stomach." (PMID 37543673, 2023). "We detected the tissue mRNA expression of IL-1β, IL-4, IL-6, and IL-10 in the esophageal adenocarcinoma rat model." (PMID 36110250, 2022). "In humans, gastric-esophageal reflux disease (GERD), Barrett’s esophagus (BE), esophageal squamous dysplasia and esophageal squamous cell carcinoma (ESCC) have all been associated with a chronic enrichment of pro-inflammatory cytokines such as IL1-β, IL-6, IL-8, and TNFα4,13–15." (PMID 37543673, 2023). "In human patients, gastric-esophageal reflux disease (GERD), Barrett’s esophagus (BE), esophageal squamous dysplasia and esophageal squamous cell carcinoma (ESCC) have been associated with increase in inflammatory cytokine stimuli such as IL-1β, IL-6, IL-8, IL-17 and TNFα4,6,9,15,48." (PMID 37543673, 2023). "Studies based on esophageal adenocarcinoma (EAC) tissues confirm the induction of EndMT by the proximity of ECs and cancer cells and by the TGF-β2 and IL-1β pathway." (PMID 40650130, 2025). "We further employed different mouse models including a genetic model of Barrett’s esophagus based on IL1β overexpression in the presence and absence of a high fat diet and deoxycholic acid to physiologically mimic gastrointestinal reflux in the mice." (PMID 36233047, 2022).
cardiac arrest (15 papers, 2010 to 2024). Cessation of breathing and/or cardiac function. "We found that the mRNA levels coding for IL-1β and IL-18 in hippocampus and cortex of post-cardiac arrest rats were downregulated after treatment with Ac-YVAD-cmk." (PMID 32703306, 2020). "The results from qRT-PCR and Western blotting showed that MCC950 significantly suppressed the levels of NLRP3, ASC, IL-1β, and IL-18 at 12 h after cardiac arrest, in both hippocampus and cortex." (PMID 32703306, 2020). "Cardiac arrest dramatically induced immediate mediators of neuroinflammation such as IL1β, TNFα, and iNOS." (PMID 28957432, 2017). "Monocyte TLR2, TLR4, IRAK3, IRAK4, NLRP3, PYCARD and IL1B were initially upregulated in patients following cardiac arrest." (PMID 27260481, 2016). "The blood levels of IL-1α and IL-1β also similarly increased after cardiac arrest in both groups." (PMID 34774087, 2021). "Consistent with this hypothesis, our data demonstrate that there is indeed intensive pyroptosis and increased caspase-1 activity in the activated microglia population after cardiac arrest, along with elevated levels of IL-1β and IL-18." (PMID 32703306, 2020). "Epoxide hydrolases are also involved in the regulation of neuroinflammation and inhibition of soluble epoxide hydrolases resulted in decreased pro-inflammatory cytokines (IL-1β and Il-6) within the context of seizures, and increased IL-10 secretion in the CNS following cardiac arrest." (PMID 29040522, 2018). "Whole blood samples taken from patients after cardiac arrest had markedly impaired synthesis of IL-1β in response to stimulation with the TLR4 agonist LPS (CAD 327.0 ± 291.3; CPR t1 31.3 ± 49.7; CPR t2 28.0 ± 35.6; CPR t3 33.5 ± 60.6 ((pg/ml)/white blood cell (WBC) count))." (PMID 27260481, 2016). "Cardiac arrest and ECPR markedly increased the plasma levels of IL-10, VEGF, leptin, TNF-α, IL-1β, IL-6, fractalkine, IL-5, IL-18, IP-10, IL-4, eotaxin, MIP-1α, IL-17α, IL-12, RANTES, G-CSF, LIX, and MCP-1." (PMID 34781966, 2021). "In analysis of time-dependent expression of monocyte mRNA in patients after cardiac arrest, significantly higher levels of TLR2, TLR4, IRAK3, NLRP3, and IL1B were observed in patients in the early hours after ROSC compared to the later phase." (PMID 27260481, 2016). "Moreover, the delivery of MCC950 led to a significant reduction in the number of CD45high CD11b+ cells accompanied by the inhibition of IL-1β and IL-18, suggesting that the intervention of NLRP3 by MCC950 prevents the post-cardiac arrest inflammatory response." (PMID 32703306, 2020). "The presence of IL-18 and IL-1β led us to hypothesize the presence and activation of the NLRP3 inflammasome in response to localized tissue injury and cardiac arrest." (PMID 26635801, 2015). "Analysis of cerebral cortex tissue using a swine specific ELISA system revealed significantly increased IL-1β protein concentration compared with the sham control group after cardiac arrest and normothermia but not after hypothermia." (PMID 20158893, 2010). "In the brain 2 h post-ROSC, cardiac arrest and CPR led to an increase in the mRNA levels of IL-6, IL-1β, and TNF-α, but not HMGB-1." (PMID 35011872, 2021).